INS (insulin)
Diseases named in the same sentence as INS in open-access papers (continued):
Sharing a sentence is not in itself a finding about the gene and the disease.
type 1 diabetes (continued). "Recent guidelines on the management of type 1 diabetes recommend that young people should be offered intensive insulin therapy in conjunction with a package of care including emotional and behavioral support." (PMID 18653444, 2008). "Type 1 diabetes (T1D) is a genetically complex disorder of glucose homeostasis that results from autoimmune destruction of the insulin-secreting cells of the pancreas." (PMID 20300303, 2008). "In type 1 diabetes therapies, the exogenous insulin replacement is generally considered as a primary treatment." (PMID 18437199, 2008). "Type 1 diabetes results from a chronic autoimmune destruction of the insulin-secreting pancreatic beta cells, probably initiated by exposure of a genetically susceptible host to an environmental agent." (PMID 18588707, 2008). "In comparison with conventional or intensive insulin treatment, islet transplantation is the only therapy for type 1 diabetes that achieves an insulin-independent, constant normoglycemic state and avoids hypoglycemic episodes." (PMID 18298656, 2008). "Hence, our present findings of decreased levels of such cardiovascular risk-markers (assuming total daily insulin-dose is a marker of insulinaemia) might translate into an improved cardiovascular outcome of metformin therapy in patients with type-1 diabetes and persistent poor glycaemic control." (PMID 18852875, 2008). "Previous studies have demonstrated an insulin-sparing effect of metformin treatment as an adjunct therapy to ongoing insulin treatment in patients with type-1 diabetes." (PMID 18852875, 2008). "There is also a potential issue concerning how the perspectives of patients using insulin pumps relate to those of patients who control their type 1 diabetes through other means." (PMID 17942385, 2007). "We thank the Juvenile Diabetes Research Foundation/Wellcome Trust Diabetes and Inflammation Laboratory (DIL) in Cambridge for sharing the type 1 diabetes insulin gene data." (PMID 17508343, 2007). "Contrasting with the common occurrence of insulin-induced hypoglycaemia in type 1 diabetes patients, deliberate overdose with insulin are rarely reported." (PMID 17963523, 2007). "It is estimated that 5-10% thereof have type 1 diabetes (T1D), which is characterized by the autoimmune destruction of the insulin-producing β-cells of the islets of Langerhans in the pancreas." (PMID 23675028, 2007). "Successful therapy for Type 1 diabetes requires that mature insulin be produced and secreted from surrogate beta-cells in a glucose-regulated manner." (PMID 17941991, 2007). "Type 1 diabetes occurs when self-reactive T lymphocytes destroy the insulin-producing islet β cells of the pancreas." (PMID 17254331, 2007). "The results reported here show significant benefits in Treatment Satisfaction and Perceived Hypoglycaemia from using insulin glargine among patients with type 1 diabetes." (PMID 17927832, 2007). "We study properties of the proposed methods by simulation and apply them to type 1 diabetes data for ASPs and their parents at candidate SNP and microsatellite marker loci in the Insulin (INS) gene region." (PMID 17508343, 2007). "Only insulin is used to treat a common disease (Type I diabetes); a few other proteins are used to treat relatively rare diseases such as growth hormone (GH) deficiency and hemophilia." (PMID 17999762, 2007). "Patients with type 1 diabetes showed an overall reduction in Perceived Hypoglycaemia, with those in the insulin glargine group showing a significantly greater reduction." (PMID 17927832, 2007). "Sample 2 was from people with Type 1 diabetes participating in a World Health Organisation study of continuous subcutaneous insulin infusion (CSII) pumps." (PMID 16817960, 2006). "The reasons for this are that patients with Type 1 diabetes need a continuing supply of insulin, syringes and monitoring, and a health care system able to provide these supplies to all parts of the country." (PMID 16504123, 2006).
type 1 diabetes (continued). "Before the discovery and purification of insulin, the average life expectancy for a patient with Type 1 diabetes was around 12 months." (PMID 16504123, 2006). "Patients with type 1 diabetes who are treated with continuous SC insulin infusion by an insulin pump should be easily converted to IV regular insulin infusion just before surgery." (PMID 15916471, 2005). "Resuming a sliding scale SC insulin treatment postoperatively has been advocated to improve metabolic control in patients with type 1 diabetes." (PMID 15916471, 2005). "On the morning of surgery patients with type 1 diabetes should receive the insulin regimen that is used intraoperatively." (PMID 15916471, 2005). "Type-1 diabetes is marked by the production of pancreatic islet β cell-specific auotantibodies and destruction of the insulin-producing β cells by autoreactive T cells." (PMID 16259622, 2005). "Insulin is the drug of choice in type – I diabetes and sulfonylureas are the drugs of choice in type II." (PMID 15745442, 2005). "Together with previous reports that proinsulin is a possible autoantigen in the development of Type 1 diabetes, the autoimmune destruction of insulin producing liver cells is a distinct possibility." (PMID 15679918, 2004). "Genetic alteration of non-pancreatic cells in a diabetic person to synthesise, store and secrete insulin in the same manner as a pancreatic β cell is a potential therapy of type 1 diabetes." (PMID 15679918, 2004). "In Type 1 diabetes, the body’s own immune system goes awry, attacking and destroying insulin-producing cells in the pancreas." (PMID 12805764, 2001). "This disease — also known as autoimmune or juvenile diabetes — strikes children suddenly, makes them dependent on insulin injections for life, and carries the constant threat of devastating complications." (PMID 12805764, 2001). "Ultimately, insulin secretion declines even further, to levels below those seen in nondiabetics (although generally still higher than those seen in type 1 diabetics)." (PMID 15706798, 1998). "T cells from individuals with type 1 diabetes recognise this peptide and it is possible that activation of the insulin-reactive cells could be stimulated by interaction with this bacterium." (PMID 41206392, 2026). "Furthermore, therapeutically targeting IL-12/IL-23 (upstream of IL-17) or IL-17 directly can help preserve insulin-producing beta cells in those newly diagnosed with Type 1 diabetes." (PMID 41613137, 2026). "Insulin, a therapeutic peptide used to treat Type I diabetes, interacts with polymers commonly found in healthcare settings via various hydrophobic interactions, which can trigger insulin agglomeration, thereby reducing its bioavailability and therapeutic efficacy." (PMID 41695414, 2026). "Furthermore, the insulin-sparing effect of GLP1RA has been recently reported in adults with new-onset type 1 diabetes." (PMID 41347115, 2026). "The major site of immune action in type 1 diabetes is in the pancreatic islets of Langerhans, which are made up of glucagon-producing alpha cells, insulin-producing beta cells, somatostatin-producing delta cells, pancreatic polypeptide-producing gamma cells and ghrelin-producing epsilon cells." (PMID 41206392, 2026). "However, a proportion of individuals with type 1 diabetes retain measurable endogenous insulin secretion, reflected by detectable C-peptide levels, several years after their initial diagnosis." (PMID 41165798, 2026). "It has been suggested that the perceived benefit of fewer basal insulin injections may be lower in individuals who also need to inject bolus insulin several times every day, as in adults with type 1 diabetes." (PMID 41048193, 2026). "Type 1 diabetes (T1D) is a chronic, progressive autoimmune disease characterised by irreversible destruction of insulin‐producing beta cells in the pancreas, which typically leads to reliance on exogenous insulin to regulate blood glucose." (PMID 41328708, 2026).
type 1 diabetes (continued). "Twelve insulin pump users with type 1 diabetes were studied using two simulation protocols." (PMID 39888427, 2025). "Similarly, autoimmune factors play a role in the progression from GDM to type 1 diabetes (T1D) in a subset of women, where the presence of autoantibodies against pancreatic islet cells can indicate an impending β-cell decline, leading to insulin dependence." (PMID 40076938, 2025). "Individuals with type 1 diabetes commonly reported poor sleep quality, irregular sleep patterns, and daytime sleepiness, all of which could negatively affect insulin sensitivity and glucose regulation." (PMID 40407447, 2025). "Despite consistent dietary adherence, this patient’s ketone levels remained at the lower end of the target range, likely due to the use of exogenous insulin for his type 1 diabetes, which may have suppressed ketogenesis." (PMID 40959698, 2025). "While prior studies have partially elucidated the role of insulin signaling in corneal nerve repair in type 1 diabetes, our preliminary data show that p-insulin receptor substrate 1 (p-IRS1) expression in diabetic corneal epithelia correlates with p-AKT levels; ADPN treatment upregulated both." (PMID 41146365, 2025). "Importantly, any fasting patient with type 1 diabetes, as diagnosed by a low C-peptide level, should be treated with intravenous insulin and glucose during the perioperative period to reduce the risk of ketosis." (PMID 40951123, 2025). "Moreover, osteosarcopenia occurs when insulin levels are low in patients with type I diabetes mellitus." (PMID 41373820, 2025). "Declining first-phase insulin secretion is a key predictor of type 1 diabetes progression." (PMID 39560746, 2025). "We hypothesise that autoimmune inflammation associated with type 1 diabetes leads to increased expression of the hepatic CEACAM1, increasing insulin clearance in rapid disease progressors." (PMID 39560746, 2025). "The objective of this study is to evaluate the effect of DPP-4 inhibitors, used as adjunct therapy with insulin, compared to placebo alongside insulin, on HbA1c, blood glucose levels, C-peptide levels, daily insulin dosage, BMI, weight change, and adverse events in patients with type 1 diabetes." (PMID 41026724, 2025). "Type 1 diabetes (T1D), specifically, is an autoimmune disorder marked by little to no insulin production and secretion due to the attack and loss of β cells by autoreactive T cells." (PMID 41480350, 2025). "In type 1 diabetes (T1D), supplementation may offer beta-cell protection against autoimmune damage, potentially slowing the progressive decline in insulin secretion." (PMID 41010515, 2025). "It is mainly manifested as non-type I diabetes with reduced insulin secretion." (PMID 40220483, 2025). "Hence, optimal insulin therapy, proper nutritional management and regular exercise appear to be suitable strategies to help individuals with type 1 diabetes to maintain or improve their mitochondrial health." (PMID 40399597, 2025). "Type 1 diabetes (T1D) is an autoimmune disease in which pancreatic B-cells are damaged by a variety of factors (autoimmunity, genetics, viral infections, etc.)and fail to secrete insulin normally." (PMID 40103816, 2025). "However, a study (n = 143) that used telephone calls and text messages to send blood glucose values, check insulin doses, and periodically monitor for acute complications in patients with type 1 diabetes observed worsening of HbA1c in 46% of patients." (PMID 40341010, 2025). "We aimed to assess the influence of body composition, energy substrate use, as well as the inherent characteristics of the disease such as insulin doses and blood glucose control, during a cardiopulmonary exercise test in subjects with uncomplicated, long‐term type 1 diabetes." (PMID 41392490, 2025). "Patients require permanent insulin therapy, managed similarly to classic type 1 diabetes." (PMID 39859105, 2025).
type 1 diabetes (continued). "Finally, hypoglycemia was similar or slightly increased with insulin icodec when compared to other long acting insulins, with again, most studies conducted in type 2 patients and much less studies conducted in type 1 diabetes." (PMID 40156735, 2025). "Type 1 diabetes results from the autoimmune destruction of β-cells, impairing insulin production." (PMID 41345203, 2025). "The level of self-management may vary between individuals with T2D and those with type 1 diabetes, potentially influenced by treatment intensity and the necessity for regular blood glucose monitoring, particularly among insulin-dependent individuals." (PMID 39841995, 2025). "Notably, these insulin concentrations are similar to basal levels observed in type 1 diabetes patients during peripheral insulin delivery." (PMID 40045281, 2025). "We hypothesized that miR-375’s expression influences insulin production and beta cell mass in type 1 diabetes, which in turn furnishes its circulating levels as an early indicator of disease development and progression." (PMID 39453571, 2025). "The advantages of advanced insulin delivery (AID) systems during pregnancy are well established: these systems can help to achieve near-desired glycemic targets while minimizing hypoglycemia in pregnant women with type 1 diabetes." (PMID 41356922, 2025). "It is suitable for patients on basal insulin with poor control or frequent hypoglycemia, but is not recommended for those with type 1 diabetes or severe insulin deficiency." (PMID 40746803, 2025). "Type 1 diabetes is characterised by a destruction of insulin-producing beta cells in the pancreas." (PMID 41224288, 2025). "Thus, while type 1 diabetes platelets generally appear to have abnormal activity, an insulin-resistant environment further amplifies platelet hyperreactivity." (PMID 40304758, 2025). "Human insulin was the most prescribed insulin among patients with type 1 diabetes." (PMID 40353123, 2025). "Type 1 diabetes (T1D) results from the autoimmune destruction of insulin-producing β-cells." (PMID 40723801, 2025). "The patient was diagnosed with type 1 diabetes and was treated with insulin degludec in combination with insulin aspartate, and he was discharged on July 19th, 2023 with the hypoglycemic regimen (insulin degludec 5 units in the morning and insulin aspartate 4 units three times a day)." (PMID 40242243, 2025). "Predominance of Type 1 diabetes participants, albeit the prerequisite of insulin therapy forces to include more Type 1 patients, may limit broad applicability." (PMID 40181799, 2025). "Following type 1 diabetes diagnosis and the initiation of insulin therapy, many patients experience partial clinical remission, characterized by improved glycemic control and lower exogenous insulin requirements due to a temporary recovery in beta cell function." (PMID 39941464, 2025). "Thus, although these cases were diagnosed as fulminant type 1 diabetes due to acute onset and insulin depletion at diagnosis, they exhibited improved insulin secretory capacity several months later." (PMID 40406776, 2025). "Type 1 diabetes is usually caused by damage to the immune system, and the insulin-producing cells are destroyed, the body no longer produces insulin or insufficient insulin is produced." (PMID 40362847, 2025). "Automated insulin delivery systems have been developed to manage type 1 diabetes." (PMID 41157817, 2025). "In patients with type 1 diabetes, adjunctive therapy with SGLT2is may reduce total insulin doses and increase ketoacidosis events because of elevated ketone levels when low doses of insulin are insufficient to inhibit lipolysis in surrounding adipose tissues." (PMID 40951123, 2025). "Type 1 Diabetes is a chronic disease of the pancreas affecting insulin production." (PMID 40076729, 2025).
type 1 diabetes (continued). "This meta‐analysis found that once‐weekly BIF provides glycaemic control comparable to daily insulin degludec but with increased mild hypoglycaemia (54–69 mg/dL) and higher event rates of clinically significant/severe hypoglycaemia—particularly in type 1 diabetes and insulin‐experienced patients." (PMID 40509887, 2025). "In this study, we used type 1 diabetes model rats injected with bolus insulin." (PMID 39899133, 2025). "Automated insulin delivery in people with type 1 diabetes and kidney failure on hemodialysis." (PMID 41174864, 2025). "Type I diabetes mellitus is an autoimmune condition where the destruction of pancreatic beta cells causes a complete lack of insulin production." (PMID 39928633, 2025). "Although the diagnosis of type 1 diabetes was initially made based on clinical manifestations, the absence of islet autoantibodies, the persistence of significant residual insulin secretion over a long period, and the remission ten years after the diagnosis led to reconsidering this diagnosis." (PMID 40290321, 2025). "People with type 1 diabetes are nearly universally managed on more complex insulin regimens, increasingly with complex support technology, and with some understanding of the concepts underlying these needed by anyone with responsibility for other aspects of their health care." (PMID 40035222, 2025). "The purpose of this study was to assess the influence of body composition, energy substrates use, as well as the inherent characteristics of the disease such as insulin doses and blood glucose control, during a cardiopulmonary exercise test in subjects with uncomplicated, long‐term type 1 diabetes." (PMID 41392490, 2025). "Also, increased production of inflammatory cytokines contributes to the decreased insulin secretion occurring before the onset of type 1 diabetes mellitus (T1DM)." (PMID 40874857, 2025). "This meta‐analysis highlights that once‐weekly basal insulin Fc provides comparable glycaemic control to daily insulin degludec but is associated with higher rates of clinically significant and severe hypoglycaemia, particularly in type 1 diabetes and insulin‐experienced patients." (PMID 40509887, 2025). "Type 1 diabetes (T1D), often diagnosed in childhood or adolescence, is a chronic autoimmune condition in which the body destroys the insulin-producing β-cells in the pancreas, resulting in insufficient insulin production." (PMID 40956852, 2025). "Despite a few clinical trials showing promising effects of immunosuppressive drugs in preserving residual beta cell function, insulin replacement therapy remains the only widely accepted treatment for people with clinical type 1 diabetes (i.e. stage 3 type 1 diabetes)." (PMID 39477880, 2025). "It is plausible that, for some individuals with type 1 diabetes, such a diet may support metabolic outcomes, including better glucose control and reduced insulin dosage." (PMID 41149081, 2025). "It is important to highlight that, according to some studies, combining metformin with insulin therapy in type 1 diabetes may positively influence EPC levels and their activity." (PMID 40710348, 2025). "CD68+ cells represented 19.6±14.3%, 9.5±8.1%, 3.9±6.9%, and 1.9±4.5% of the total cells in the peri-islet regions of the type 1 diabetes ICI, type 1 diabetes insulin-deficient islets (IDI), Aab+, and non-diabetic groups, respectively." (PMID 41000615, 2025). "In ambulatory care, CGM has been widely adopted as standard practice for adults using basal insulin, multiple daily injections, or continuous subcutaneous insulin infusion, as well as for youth with type 1 diabetes, owing to its demonstrated benefits for glycemic control and treatment satisfaction." (PMID 41517284, 2025). "As hypothesized, higher burden scores were observed in patients facing greater treatment complexity (e.g., type 1 diabetes, intensive insulin therapy), greater digital tool use, and greater social vulnerability." (PMID 40894032, 2025).